MIAT (myocardial infarction associated transcript)
Diseases named in the same sentence as MIAT in open-access papers (continued):
Sharing a sentence is not in itself a finding about the gene and the disease.
papillary thyroid cancer (6 papers, 2019 to 2023). "For instance, myocardial infarction-associated transcript (MIAT) promotes proliferation, migration and invasion in papillary thyroid carcinoma cells." (PMID 36934152, 2023). "Similarly, MIAT upregulation was observed in both papillary thyroid cancer (PTC) tissues and cell lines, and its overexpression was closely associated with advanced tumor stage and lymph node metastasis." (PMID 32274858, 2020).
acute myeloid leukemia (5 papers, 2016 to 2023). Acute myeloid leukemia (AML) is a group of neoplasms arising from precursor cells committed to the myeloid cell-line differentiation. "Acute myeloid leukemia and ovarian cancer upregulate MIAT, increasing the proliferation by sponging miR-495 and miR-330-5p, respectively." (PMID 37190145, 2023). "In addition, further research highlighted the importance of MIAT in progression of acute myeloid leukemia (AML) as it was reported to sponge miR-495, affecting further downstream target protein production." (PMID 37624039, 2023). "Moreover, MIAT knockdown suppresses the progression of acute myeloid leukemia in immunodeficient NOD-SCID mice." (PMID 37190145, 2023).
Alzheimer disease (5 papers, 2016 to 2024). A progressive, neurodegenerative disease characterized by loss of function and death of nerve cells in several areas of the brain leading to loss of cognitive function such as memory and language. "We showed that MIAT was implicated in the vasculo-neuronal dysfunction and degeneration in Alzheimer's disease." (PMID 27391072, 2016). "We show that MIAT knockdown leads to cerebral microvascular degeneration, progressive neuronal loss and neurodegeneration, and behavioral deficits in a CNS neurovascular disorder, Alzheimer's disease." (PMID 27391072, 2016). "MIAT expression was significantly down-regulated in the brain parenchyma of Alzheimer's disease transgenic mice." (PMID 27391072, 2016). "In addition, aberrant expression of MIAT is observed in neurovascular dysfunction contributing to the pathogenesis of Alzheimer’s disease." (PMID 30898084, 2019). "We also determined the role of MIAT in vasculo-neuronal dysfunction in Alzheimer's disease." (PMID 27391072, 2016). "MIAT also plays a role as a regulator of neural and vascular cell function via the MIAT/miR-150-5p/VEGF network, and its knockdown causes cerebral microvascular degeneration, progressive neuronal loss and neurodegeneration, and behavioral deficits in Alzheimer’s disease." (PMID 33799572, 2021).
breast tumors (5 papers, 2017 to 2023). "Here, we found that MIAT expression was higher in breast tumors of the luminal subtype compared to the other subtypes." (PMID 34209776, 2021). "Previous studies have reported an increased in MIAT expression levels in high-grade breast tumors compared with low-grade ones." (PMID 29914974, 2018). "The results revealed that the overall mean of MIAT expression level was significantly higher in breast tumor compared with the mean of MIAT expression levels in normal breast tissue." (PMID 29914974, 2018). "Similarly, MIAT expression is upregulated in high-grade breast tumors, as well as ER- and Her2-positive tumor tissues." (PMID 37025425, 2023). "Next, we investigated the expression of MIAT in human breast tumor tissue microarrays (TMA)." (PMID 29100300, 2017). "Data from TCGA showed that compared to normal tissue, MIAT was up-regulated, while KCNQ1OT1, LOC100270804, and FLJ10038 were down-regulated in breast tumor tissues." (PMID 34209776, 2021).
diabetic retinopathy (5 papers, 2018 to 2024). "For instance, lncRNAs such as MALAT1 and MIAT have been extensively studied and demonstrated to be involved in the pathogenesis of diabetic retinopathy." (PMID 38907191, 2024).
lung adenocarcinoma (5 papers, 2017 to 2023). A carcinoma that arises from the lung and is characterized by the presence of malignant glandular epithelial cells. "Besides, MIAT was associated with the development of lung adenocarcinoma." (PMID 29540201, 2018). "MIAT may promote the development of lung adenocarcinoma via the MIAT-miR-106-MAPK signalling pathway loop." (PMID 28738804, 2017).
thyroid cancer (5 papers, 2019 to 2023). "Our study provides novel insight into the role of MIAT in cancer and may aid in the development of diagnostic and therapeutic tools for thyroid cancer treatment and diagnosis." (PMID 34811354, 2021). "High-level expression of MIAT, a lncRNA, is found in thyroid cancer progression that has a positive correlation with EZH2 (enhancer of zest homolog 2)." (PMID 37924077, 2023). "The up-regulation of MIAT sponges miR-150 and causes induction of EZH2 expression and thyroid cancer cell migration." (PMID 37924077, 2023). "Among them, miR-324-3p harbors a potential binding site for MIAT and its expression is negatively correlated (r = − 0.365, p < 0.000) with MIAT levels in expression data of 509 thyroid carcinoma tissues (THCA) from TCGA." (PMID 31372094, 2019). "Additionally, in thyroid cancer, MIAT contributes to tumor progression by absorbing miR-150-5p and modulate EZH2." (PMID 36941990, 2023). "We further investigated whether metastasis ability of thyroid cancer cells could function via mediating miR-150-5p in the situation with pcDNA3.1, pc-MIAT, pc-MIAT + miR-150-5p, and pc-MIAT + anti-miR-150-5p." (PMID 34811354, 2021). "Upregulation of MIAT and EZH2 were positively related with LNM, high risk, recurrence and RAS mutation which indicates that MIAT and EZH2 may be played an important role in thyroid cancer progression." (PMID 34811354, 2021).
Anxiety (4 papers, 2017 to 2025). Intense feelings of nervousness, tension, or panic often arise in response to interpersonal stresses. "Another is MIAT (also known as GONAFU); RNA levels were found to be expressed at higher levels in parvalbumin GABAergic interneurons in SZ subjects and have been found to regulate fear-related anxiety traits in mice." (PMID 28321286, 2017).
glioma (4 papers, 2017 to 2023). A benign or malignant brain and spinal cord tumor that arises from glial cells (astrocytes, oligodendrocytes, ependymal cells). "In the present study, we try to provide a novel strategy for glioma therapy basing on the understanding the interaction between MIAT, miR-140-3p, ZAK, and NFκB-p65 factors and BTB permeability." (PMID 33127881, 2020). "Further analysis of TCGA and GEO data revealed that the expressions of PVT1 and CYTOR were up-regulated, while HAR1A and MIAT expressions were down-regulated in gliomas." (PMID 29108264, 2017). "Our studies first identified differentially expressed lncRNAs in glioma based on gene expression profiling, and focused on the lncRNAs PVT1, CYTOR, HAR1A and MIAT for further analysis." (PMID 29108264, 2017). "This study focused on identifying differentially expressed lncRNAs in gliomas based on gene expression profiling, and chose certain lncRNAs PVT1, CYTOR, HAR1A and MIAT, which changed with significant differences." (PMID 29108264, 2017). "In support of this interpretation, Miat was found to regulate the NGS gene Gria2 in transgenic mouse MB, but MIAT (the human orthologue of Miat) was found not to regulate any NGS genes in these glioma datasets." (PMID 37693314, 2023). "In this study, we demonstrated that MIAT, ZAK, and phosphorylated NFκB-p65 (p-NFκB-p65) were upregulated, while miR-140-3p was downregulated in glioma-exposed endothelial cells (GECs) of BTB compared with those in endothelial cells cocultured with astrocytes (ECs) of blood–brain barrier (BBB)." (PMID 33127881, 2020). "The expressions of HAR1A and MIAT were significantly decreased in glioma samples compared to non-tumor controls (both P <0.001)." (PMID 29108264, 2017).
heart failure (4 papers, 2016 to 2026). Inability of the heart to pump blood at an adequate rate to meet tissue metabolic requirements. "Despite growing evidence from human and rodent studies implicating MIAT in heart failure, the upstream regulatory pathways controlling its expression remain poorly defined." (PMID 41764204, 2026). "Additionally, we examined the expression levels of three known heart failure-related lncRNAs, LIPCAR, MIAT and ANRIL." (PMID 28040802, 2016).
Hyperglycemia (4 papers, 2017 to 2022). An increased concentration of glucose in the blood. "As a result of miR-130a-3p/TLR4 crosstalk, MIAT knockdown protected podocytes from hyperglycemia-induced damage." (PMID 36618403, 2022). "Our findings further verified that hyperglycemia triggers upregulation of MIAT expression in a time-dependent manner in the retinas of diabetic rats." (PMID 32210708, 2020). "In diabetic rats, hyperglycemia significantly up-regulates MIAT levels; miR-150-5p knockdown can further increase MIAT levels." (PMID 29074557, 2017). "Reduced MIAT expression restores slit-diaphragm integrity, attenuates foot process effacement, prevents dedifferentiation, and suppresses mitogenic catastrophe in podocytes during hyperglycemia." (PMID 36618403, 2022). "Our findings indicated that cardiomyocyte apoptosis was increased in diabetic rats, whereas MIAT knockdown could attenuate apoptosis induced by hyperglycemia." (PMID 28703801, 2017).
leukemia (4 papers, 2016 to 2023). A malignant (clonal) hematologic disorder, involving hematopoietic stem cells and characterized by the presence of primitive or atypical myeloid or lymphoid cells in the bone marrow and the blood. "Nevertheless, despite ongoing efforts to further elucidate the role of MIAT in carcinogenesis and cancer-related processes, little is known about the interconnection between MIAT and leukemia." (PMID 37624039, 2023). "Here, we determined the expression level of MIAT in established leukemia/lymphoma cell lines and found its upregulation in lymphoid but not in myeloid cell lineage with mature B cell phenotype." (PMID 27527866, 2016). "Our observations suggest that MIAT could act as an oncogene and it has the potential to be used not only as a reliable biomarker for leukemia, but also be employed for prognostic and therapeutic purposes." (PMID 37624039, 2023).
lymphoma (4 papers, 2016 to 2022). A malignant (clonal) proliferation of B- lymphocytes or T- lymphocytes which involves the lymph nodes, bone marrow and/or extranodal sites. "Although MIAT expression is restricted to several subsets of neurons, MIAT up-regulation has been detected in a number of mature B cell leukemia/lymphoma cell lines and in primary CLL cells." (PMID 36362925, 2022). "We further show that, as previously reported in mouse embryonic stem cells, MIAT in DLBL lymphoma cells constitutes a similar regulatory loop with OCT4 and in lymphoma, both MIAT and OCT4 are essential for cell survival." (PMID 27527866, 2016).
neuroblastoma (4 papers, 2017 to 2023). Neuroblastoma (NB) is the most common solid, extracranial childhood tumor. "In a recent study where differentiated SH-SY5Y neuroblastoma cells were treated with BDNF and subjected to microarray studies, several lncRNAs including MALAT1/NEAT2 and MIAT/GOMAFU were found to differentially expressed." (PMID 29109677, 2017).
Sepsis (4 papers, 2018 to 2021). Sepsis is defined as life-threatening organ dysfunction caused by a dysregulated host response to infection. "Up-regulation of MIAT promoted apoptosis in sepsis-related kidney injury." (PMID 34956235, 2021). "To assess the chromosomal origins and the relative impact of MIAT’s contributions to inflammation, we segregated the predicted MIAT miR targets according to their chromosomal origins and reported clinical associations, and identified a complex profile of MIAT’s contribution to MetS and sepsis." (PMID 29922126, 2018). "NEAT1, MALAT1, THRIL, XIST, MIAT and TUG1 are among lncRNAs that participate in the pathoetiology of sepsis-related complications." (PMID 34956235, 2021).
atrial fibrillation (3 papers, 2022 to 2024). A disorder characterized by an electrocardiographic finding of a supraventricular arrhythmia characterized by the replacement of consistent P waves by rapid oscillations or fibrillatory waves that vary in size, shape and timing and are accompanied by an irregular ventricular response. "CXCL-10-overexpression promotes structural remodeling and consequently atrial fibrillation, therefore increased levels of MIAT in circulating EV might indicate a disease progression in AF patients." (PMID 39314768, 2024).
cardiac interstitial fibrosis (3 papers, 2017 to 2022). "In a mouse model of MI, we found that MIAT was remarkably up-regulated, which was accompanied by cardiac interstitial fibrosis." (PMID 28198439, 2017). "Additionally, Wisper, CHRF, AK081284, MEG3 and MIAT are also important pro-fibrotic lncRNAs in cardiac interstitial fibrosis and act via diverse regulatory mechanisms." (PMID 36384975, 2022). "Similarly, the MIAT levels increase in response to hypoxia, and MIAT is involved in cardiac interstitial fibrosis." (PMID 34026872, 2021).
colon cancer (3 papers, 2018 to 2024). "The RT-qPCR assay showed that the expressions of MIAT were upregulated compared to colon cancer adjacent tissues, while hsa-miR-532-3p was downregulated." (PMID 35607443, 2022).
diabetic nephropathy (3 papers, 2019 to 2025). "In 2021, researchers observed that the lncRNA MIAT was noticeably upregulated in the plasma and kidney tissues of patients with diabetic nephropathy, and this upregulation correlated with higher albumin/creatinine ratios and serum creatinine levels." (PMID 40246828, 2025). "Thus, the MIAT/miR-147a/E2F3 axis may promote cellular proliferation and fibrosis in the progression of diabetic nephropathy." (PMID 40282196, 2025).
fibrosis (3 papers, 2017 to 2025). the formation of excess fibrous connective tissue in an organ or tissue in a reparative or reactive process. "For instance, MIAT has been shown to modulate cardiac fibrosis by serving as a ceRNA and negatively regulating multiple miRNAs, such as miR-29a-3p, miR-24, or miR-214-3p." (PMID 39379100, 2024).
Hypertension (3 papers, 2019 to 2025). The presence of chronic increased pressure in the systemic arterial system. "MIAT expression was significantly associated with hypertension, IA location, and IA rupture status." (PMID 40321069, 2025). "Both MIAT and MALAT1 expressionlevels were associated with hypertension and premature CAD." (PMID 31188931, 2019).
leiomyoma (3 papers, 2024 to 2025). A well-circumscribed benign smooth muscle neoplasm characterized by the presence of spindle cells with cigar-shaped nuclei, interlacing fascicles, and a whorled pattern. "In addition, the expression of MIAT correlated with the MED12 mutation status of the leiomyomas, and knock down of MIAT in leiomyoma smooth muscle cells’ spheroids blocked the effects of TGF-β3 on the induction of COL1A1 and COL3A1 expression." (PMID 38279317, 2024). "Our previous studies identified a profibrotic network involving MIAT, miR-29, TGF-β3, and collagens in leiomyomas, which forms a positive feedback loop that causes continuous fibrosis and the growth of leiomyomas." (PMID 39519092, 2024). "Additionally, the expression of cell cycle regulatory genes, such as CCND1, CDK2, and E2F1, was significantly reduced, further supporting the potential of MIAT as a therapeutic target for fibroid treatment." (PMID 40862769, 2025). "In fact, the lncRNAs MIAT and XIST have been shown to be potential therapeutic targets in fibroids." (PMID 40862769, 2025).
autoimmune disease (2 papers, 2022 to 2024). A disorder resulting from loss of function or tissue destruction of an organ or multiple organs, arising from humoral or cellular immune responses of the individual to their own tissue constituents. "To determine if MIAT induction is involved in other autoimmune diseases, we analyzed its expression in a microarray dataset from psoriasis patients." (PMID 35784351, 2022). "MIAT, as an autoimmune disease-related gene, has a particular function in immune cells." (PMID 39317938, 2024). "Interestingly, the treatment with brodalumab, a competitive inhibitor of the IL-17 receptor A subunit, reduced MIAT expression in psoriatic skin lesions, suggesting MIAT is involved in other Th17 related autoimmune disorders." (PMID 35784351, 2022). "Interestingly, MIAT was highly expressed in T cells of RA patient synovial biopsies and psoriatic skin lesions, suggesting a role in autoimmune diseases." (PMID 35784351, 2022). "Further work is needed to understand the function of MIAT in Th17-mediated autoimmune disease." (PMID 35784351, 2022).
cataract (2 papers, 2016 to 2018). Partial or complete opacity of the crystalline lens of one or both eyes that decreases visual acuity and eventually results in blindness. "MIAT level was significantly up‐regulated in the AH of cataract patients." (PMID 26818536, 2016). "To determine whether circulating MIAT is specifically up‐regulated in patients with cataract, we collected whole blood from cataract patients, PVR patients, glaucoma patients, and age‐matched controls." (PMID 26818536, 2016). "As MIAT is up‐regulated in the pathological tissue of cataract patients, we have been suggested that its circulating level was also up‐regulated in patients with cataract." (PMID 26818536, 2016). "MIAT level was significantly up‐regulated in the plasma fraction of cataract patients, but not in other individuals." (PMID 26818536, 2016). "MIAT level was significantly up‐regulated in the AH of cataract patients, but not in other patients with glaucoma, PVR, or trauma." (PMID 26818536, 2016).
clear cell renal cell carcinoma (2 papers, 2020 to 2023). "MIAT is overexpressed in clear cell renal cell carcinoma (CCRCC) and associated with poor prognosis." (PMID 32591022, 2020).
Coronary Artery Disease (2 papers, 2019 to 2022). "Our results showed that serum MIAT levels in patients with coronary heart disease remained at a relatively high level." (PMID 31143478, 2019). "In this study, we studied the expression of MIAT in peripheral blood of patients with coronary heart disease and its clinical significance, which might provide a new idea for the prevention and treatment of coronary heart disease." (PMID 31143478, 2019).
esophageal squamous cell carcinoma (2 papers, 2020 to 2021). Esophageal squamous cell carcinoma (ESCC) is a type of esophageal carcinoma (EC) that can affect any part of the esophagus, but is usually located in the upper or middle third. "In esophageal squamous cell carcinoma (ESCC), SOX2 binds to the MIAT promoter region to promote MIAT expression." (PMID 35070996, 2021).
gastric adenoma (2 papers, 2020 to 2025). A neoplastic polyp that arises from the stomach. "The expression level of serum exosomal MIAT was markedly higher in GC patients than in gastric adenoma patients (P < .001) and healthy controls (P < .001)." (PMID 32274858, 2020).
liver cancer (2 papers, 2021 to 2023). An epithelial or non-epithelial malignant neoplasm that arises from the liver. "Similarly, in liver cancer, MIAT interacts with miR-520d-3p and miR-214, affecting EPHA2 and hepatoma-derived growth factor (HDGF) expression, respectively." (PMID 37624039, 2023).